RBP4 (retinol binding protein 4)
Diseases named in the same sentence as RBP4 in open-access papers (continued):
Sharing a sentence is not in itself a finding about the gene and the disease.
metabolic syndrome (continued). "Analysis of 1489 subjects (26.9% HDL-C dyslipidemia) identified rs3758539, a non-coding variant in the 5’UTR of RBP4, to be associated with HDL-C dyslipidemia (odds ratio = 1.45, 95% confidence interval = 1.08–1.97, p = 0.01)." (PMID 30497399, 2018). "Improvement of metabolic syndrome with diet therapy and bariatric surgery decreased serum RBP4 concentrations." (PMID 30374329, 2018). "It reports a functional variant in the promoter of RBP4, a gene directly involved in lipoprotein metabolism, to be associated with HDL-C dyslipidemia." (PMID 30497399, 2018). "Many studies have shown that serum RBP4 levels correlate with several components of metabolic syndromes in humans, including hypertension, dyslipidemia, cardiovascular disease, and intra-abdominal fat mass." (PMID 25918733, 2015). "Retinol binding protein-4 (RBP-4) is another metabolic syndrome-related biomarker, also considered a new potential cardiometabolic risk factor." (PMID 24757680, 2014). "Most research on RBP4 to date is in the fields of metabolic syndromes and cardiovascular diseases." (PMID 37510153, 2023). "Furthermore, multivariate models were constructed using age, sex, BMI, metabolic syndrome, and plasma RBP4 level." (PMID 37510153, 2023). "SdLDL was found to be an independent predictor of RBP4 in patients with dyslipidemia." (PMID 35309061, 2022). "Besides, positive associations were also observed between RBP4 and traditional CVD risk factors, including dyslipidemia, hypertension, metabolic syndrome, and coronary artery calcification." (PMID 35369314, 2022). "Retinol binding protein (RBP-4) is an adipocyte-derived factor and a member of the lipocalin family that plays a role as a vitamin A carrier in the blood and is functionally involved in insulin resistance (type 2 diabetes) and metabolic syndrome (MetS)." (PMID 33776572, 2021). "Interestingly, RBP4 possibly correlates with an increased regain of lost weight and is one of the predictors of metabolic syndrome among people with excessive body weight." (PMID 32718041, 2020). "Additionally, RBP4 can also be a predictor for the diagnosis of metabolic syndrome and weight regain." (PMID 32718041, 2020). "The relationships between RBP4 levels, the established adipokines (leptin and adiponectin) and the components of MS were examined in 3445 school-aged children recruited in 2004 for the Beijing Child and Adolescent Metabolic Syndrome study." (PMID 29759068, 2018). "Interestingly, RBP4 levels were significantly correlated also with serum cholesterol and serum triglyceride thus confirming its link with IR and metabolic syndrome." (PMID 29333450, 2017). "Finally we found a positive correlation between RBP4 and heart rate an indirect marker of adrenergic drive hyperactivation that invariably characterizes the different aspects of the metabolic syndrome." (PMID 29333450, 2017). "This association was independent of BMI, lipids, and glucose, suggesting that mechanisms other than components of metabolic syndrome may contribute to the link between RBP4 and breast cancer." (PMID 28002423, 2016). "Based on that, we suggest that the upregulation of Rbp4 may be related to development of metabolic syndrome in ISIAH rats, too." (PMID 26821914, 2016). "Similarly, oxidative stress plays a vital role in numerous metabolic abnormalities observed in metabolic syndrome and tends to correlate with RBP4 levels." (PMID 26842399, 2016). "Indeed a role for RBP4 in the catabolism of very low-density lipoprotein (VLDL) and the formation of sdLDL has been suggested, though the implication of RBP4 in components of atherogenic dyslipidemia has been studied very little." (PMID 24223837, 2013). "Using a multiple logistic regression model, independent significant risk factors for subclinical atherosclerosis were identified, including age, sex, BMI, smoking status, FPG, fasting insulin, presence of hypertension, presence of dyslipidemia and lipocalin-2 or RBP4." (PMID 23799122, 2013).
metabolic syndrome (continued). "Moreover, excess serum levels of vitamin A could also increase the transport of retinol-binding protein 4 (RBP4), subsequently increasing the risk of CHD, stroke, metabolic syndrome, and cardiovascular risk factors, including triglycerides and hypertension." (PMID 40791230, 2025). "Similarly, sdLDL was found to be an independent predictor of oxidized low-density lipoprotein (ox-LDL) in patients with dyslipidemia, and sdLDL may be an important link between RBP4 and ox-LDL." (PMID 35309061, 2022). "Several studies have also shown a correlation between RBP4 and other components of human metabolic syndrome (MetS), such as dyslipidaemia, hypertension and cardiovascular diseases." (PMID 32095874, 2020). "Furthermore, the RBP4/adiponectin ratio was significantly increased among individuals with nascent metabolic syndrome and, thus, could constitute a predictor of CVD in this patient group in large, prospective studies." (PMID 32718041, 2020). "As a consequence, T2DM subjects with rather mild hyperglycemia and dyslipidemia were preferentially included, which could to some extent mask relationships of RBP4 with dysglycemia and could underestimate relationships of RBP4 with (apo)lipoproteins and lipoprotein subfractions." (PMID 31717719, 2019). "In addition, retinol-binding protein 4 (RBP4) is an adipose tissue-derived cytokine that transports retinol from the liver to various tissues and it is related to insulin resistance, visceral fat distribution, and dyslipidemia." (PMID 29785210, 2018). "In PLHIV, higher levels of RBP4 were detected in those patients with metabolic syndrome (MetS), and a positive correlation between circulating RBP4 concentrations and the number of components of MetS was identified." (PMID 35216318, 2022). "Pearson correlation coefficients were used to assess the relationship between RBP4, TTR, and HOMA-IR, with metabolic syndrome parameters." (PMID 29747616, 2018). "Another 10-year study of 352 children showed significantly higher baseline RBP4 levels in children with persistent metabolic syndrome (42.1 μg/mL) than in those who never exhibited any sign of metabolic syndrome (32.7 μg/mL)." (PMID 37510153, 2023). "In addition, group B (HOMA-IR ≥ 2.5) had significantly more preoperative biomarker abnormalities (other than dyslipidemia) than group A, including leptin, ghrelin, PYY, insulin, RBP4, and LGr." (PMID 36203073, 2022). "Retinol-binding protein 4 (RBP4), which is synthesized by the liver and released into the blood, has been identified to be related to the development of metabolic syndrome, atherosclerosis, and hypothyroidism, owing to its interaction with retinol, thyroxine transporter, and cell surface receptors." (PMID 33503180, 2021). "RBP4 contributes to HUA–induced IR, at least partially by inhibiting the phosphorylation of the IRS/PI3K/Akt signaling pathway in adipocytes, and thereby affecting glucose uptake and inducing metabolic syndrome." (PMID 34177800, 2021). "Moreover, a relationship between RBP4, TTR and metabolic syndrome components was found in this study." (PMID 29747616, 2018). "RBP4 levels were higher in women suffering from metabolic syndrome or impaired glucose metabolism, but ROC curve analysis showed that plasma RBP4 does not appear to be a clinically useful parameter to predict metabolic consequences in PCOS women." (PMID 27473078, 2017). "However, several studies have reported negative correlations between the serum levels of HDL-C and RBP4, and thus further research is warranted to assign a causal relationship between rs3758539 and HDL-C dyslipidemia." (PMID 30497399, 2018). "However, some studies found that serum RBP4 levels were not relevant with all of these parameters of metabolic syndrome." (PMID 28002423, 2016).
metabolic syndrome (continued). "Together, the results presented here indicate that prolonged fructose consumption may contribute to the development of the metabolic syndrome by increasing circulating concentrations of uric acid, GGT activity (altered hepatic function), and the production of RBP-4." (PMID 22828276, 2012). "Elevated retinol-binding protein 4 (RBP4) levels may contribute to the development of metabolic abnormalities, but prospective studies evaluating the association between childhood RBP4 levels and metabolic syndrome (MS) in adulthood are lacking." (PMID 29759068, 2018).
atherosclerosis (56 papers, 2012 to 2025). A disease characterized by the build-up of fatty material and calcium deposition in the arterial wall resulting in partial or complete occlusion of the arterial lumen. "Adipokines, including adiponectin, leptin, resistin, omentin, visfatin, chemoattractant and retinol binding protein 4, are considered to be risk factors for atherosclerosis." (PMID 34122426, 2021). "Recent clinical studies have also linked higher circulating RBP4 to cardiovascular diseases, including hypertension, heart failure, and atherosclerosis." (PMID 31278889, 2019). "Meanwhile, emerging evidences have linked elevated level of serum RBP4 to cardiovascular diseases, such as atherosclerosis, hypertension, and coronary artery diseases (CAD), on the basis of population-based studies." (PMID 30186876, 2018). "RBP4 concentrations were independently associated with enhanced atherosclerosis in RA patients with generalized or/and abdominal obesity." (PMID 24651174, 2014). "High RBP4 concentrations are associated with increased atherosclerosis and incident coronary event rates." (PMID 24651174, 2014). "In this study we evaluated the association of CIMT, an established marker of subclinical atherosclerosis, with RBP4 and total and HMW adiponectin in type 2 diabetic patients without clinical evidence of atherosclerotic vascular disease." (PMID 23497488, 2012). "The purpose of the current study was to examine the associations of RBP4 with both standard CVD risk factors as well as subclinical atherosclerosis in healthy mid-life women screened for the Kronos Early Estrogen Prevention Study (KEEPS)." (PMID 22587616, 2012). "Notably, in addition to facilitating atherosclerosis development, RBP4 also facilitates neuronal loss." (PMID 37808505, 2023). "Moreover, they were all positively associated with RBP4, indicating that RBP4 participates in the formation of atherosclerosis by the JAK2/STAT3 signaling pathway." (PMID 35082965, 2022). "Studies have shown that RBP4 is not only associated with obesity and diabetes but also causes risk factors for cardiovascular and cerebrovascular diseases such as metabolic syndrome, atherosclerosis, and coronary heart disease." (PMID 36043144, 2022). "Besides being associated with obesity, hypertension, insulin resistance, and diabetes, RBP4 is also a risk factor for cardiovascular diseases, such as metabolic syndrome, atherosclerosis, and coronary heart disease." (PMID 36304097, 2022). "Among them, leptin, resistin, visfatin, chemoattractant and retinol binding protein 4 may be the common pathogenic factors of psoriasis and atherosclerosis." (PMID 34122426, 2021). "Elevated RBP-4 levels are known to be linked to IR, T2D, atherosclerosis, and CAD." (PMID 34571734, 2021). "Interestingly in this regard, we recently documented that RBP4 concentrations are paradoxically associated with reduced endothelial activation and, at the same time, also with enhanced atherosclerosis in RA." (PMID 24994945, 2014). "Moreover, RBP4 levels have been positively associated with carotid intima-media thickness, metabolic complications, atherosclerosis." (PMID 25479076, 2014). "The significant association between lipocalin-2 or RBP4 and subclinical atherosclerosis remained unchanged after the HOMA-IR was taken into consideration when performing regression (OR 2.18, 95% CI 1.08–4.38, P = 0.029; OR 1.17, 95% CI 1.11–1.24, P<0.001, respectively)." (PMID 23799122, 2013). "A study on clinically healthy European elder people hypothesized that vitamin A could be linked with atherosclerosis, endothelial function and left ventricular function, based on the new findings that RBP4 concentration correlates with subclinical inflammation in the early stages of infant obesity." (PMID 32283588, 2020).
atherosclerosis (continued). "It has been demonstrated that RBP4 expression was enhanced in the areas rich in macrophage foam cells in atherosclerotic lesions of aortic specimens from both humans and apolipoprotein E-deficient mice, suggesting foam cell-like formation in our biomimetic atherosclerosis models." (PMID 32947976, 2020). "RBP4 stimulates the expression of adhesion molecules in the endothelial cells, promoting the progress of atherosclerosis and arterial hypertension." (PMID 38256272, 2024). "It was discovered that there was an inverse relationship between carotid intima-media and plaque echogenicity, suggesting a potential link between RBP4 and the onset of atherosclerosis." (PMID 39558976, 2024). "As we know, RBP4 is a predictor of endothelial dysfunction, atherosclerosis and other cardiovascular diseases and is a member of the lipocalin family, which is bound to vitamin A and transthyretin while being secreted into the circulation." (PMID 38069063, 2023). "Considering that both lipid excess and inflammation aggravate the development of atherosclerosis, serum RBP4 has been positively correlated with CVD and the diagnosis of recurrent stroke in stroke patients." (PMID 37808505, 2023). "In conclusion, the serum levels of RBP4 were significantly elevated in elderly patients with cerebral infarction and correlated with oxidative stress injury and the degree of atherosclerosis." (PMID 36304097, 2022). "Some studies have shown that serum RBP4 can promote macrovascular disease, which is related to atherosclerosis and can be used to predict clinical cardiovascular disease." (PMID 36043144, 2022). "The serum levels of RBP4 were significantly elevated in elderly patients with cerebral infarction and correlated with oxidative stress injury and the degree of atherosclerosis." (PMID 36304097, 2022). "Studies have discovered that RBP4 can improve atherosclerosis by influencing the metabolism of lipid and glucose and further changing the stability of coronary plaques." (PMID 34956579, 2021). "RBP4 is an adipokine with an established role in atherosclerosis, while adiponectin has unique anti-inflammatory properties." (PMID 34758835, 2021). "Adipokines retinol-binding protein 4 (RBP4), resistin, and leptin are reported to support the progression of atherosclerosis, while adiponectin has protective actions against plaque formation." (PMID 32947976, 2020). "It has been demonstrated that patients with atherosclerosis of carotid arteries in combination with IHD have higher levels of RBP4." (PMID 32121175, 2020). "Further studies have proved that RBP4 links to insulin resistance, diabetes and atherosclerosis, retinol being inversely corelated with cIMT." (PMID 32283588, 2020). "A recent study showed that elevated RBP4 facilitated macrophage-derived foam cell formation through activating cholesterol uptake, and thus accelerated atherosclerosis progression." (PMID 31278889, 2019). "The median RBP4 levels were significantly greater for atherosclerosis than for the other stroke subtype groups (32.8 (IQR: 22.8-42.7) μg/ml compared with 25.4 (IQR: 17.5–35.5) μg/ml, respectively; P<0.001)." (PMID 30038059, 2018). "The purposes of this study were to evaluate the expression of retinol-binding protein 4 (RBP4) in diabetic rats with atherosclerosis and to investigate the role of vitamin D intervention." (PMID 30186876, 2018). "In the present study, we found that the levels of adipose tissue and serum RBP4 in the DM groups especially in the diabetic atherosclerosis group were higher than those in the NC group." (PMID 30186876, 2018). "Although, the association of RBP4 with an increased risk of CVD has been proposed, its prognostic value in carotid or coronary atherosclerosis progression still lacks consensus." (PMID 30038059, 2018). "Recently, RBP4, an adipocytokine related to IR, has been suggested to play an important role in the occurrence and development of atherosclerosis and CVD." (PMID 24604418, 2014).